CD4 (CD4 molecule)
Diseases named in the same sentence as CD4 in open-access papers (continued):
Sharing a sentence is not in itself a finding about the gene and the disease.
rheumatoid arthritis (continued). "MSC-induced CD4+ Tregs maintained a regulatory phenotype and function over time and suppressed the ex vivo proliferation of T cells from patients with rheumatoid arthritis in an antigen-specific manner." (PMID 33643298, 2020). "Against this background, we evaluated the intracytoplasmic CD4+ T cell cytokine patterns in rheumatoid arthritis patients in Ghana and determined their relationship with disease activity." (PMID 33101416, 2020). "Here, the authors generate ATAC-seq, Hi-C, Capture Hi-C and RNA-seq data in stimulated CD4+ T cells to identify functional enhancers and demonstrate interactions of expression quantitative trait loci with target genes in rheumatoid arthritis." (PMID 32879318, 2020). "MSC downregulated the proliferation and differentiation of TFH cells during in vitro polarizing conditioning of CD4+ T cells isolated from patients with rheumatoid arthritis and Sjogren syndrome, or from lupus-prone mice." (PMID 33643298, 2020). "As the indirect antigen presenting cells and co-stimulatory signaling transducer, CD14+ monocytes induced the activation and differentiation of CD4+ T cells in rheumatoid arthritis, lung squamous carcinoma, and chronic hepatitis C." (PMID 32276581, 2020). "The number of CD4+CD28− T cells measured by sorting is higher in patients who initially meet ACR classification criteria for rheumatoid arthritis (RA) compared to those who were classified as undifferentiated arthritis (UA)." (PMID 33291545, 2020). "Recently, the presence of CD4+ T cells reactive to citrullinated aggrecan epitopes in patients with rheumatoid arthritis (RA) has been described." (PMID 33277543, 2020). "Interleukin-21 (IL-21), produced by stimulated CD4+ T immune cells, plays a significant role in the progression of rheumatoid arthritis (RA) via induction of inflammatory factors and matrix metalloproteinases (MMPs) such as MMP-3 and MMP-13." (PMID 32380783, 2020). "In 2017, a new subset of IL‐21‐producing memory CD4+ helper T cells was shown to be strongly expanded in the synovial fluid of seropositive rheumatoid arthritis patients." (PMID 32697399, 2020). "CD4+ T cells play a central role during the early stages of rheumatoid arthritis (RA), but to which extent they are required for the perpetuation of the disease is still not fully understood." (PMID 32345366, 2020). "Here, we evaluated the intracytoplasmic CD4+ T cell cytokine patterns in rheumatoid arthritis patients in Ghana and determined their relationship with disease activity." (PMID 33101416, 2020). "In rheumatoid arthritis, the CD4+CXCR3+CCR6+ subset is known to express high levels of IFNγ with poor secretion of IL-17A,36 though we did not observe any associated cytokine profile in our remission patients." (PMID 31540934, 2019). "Bone loss is enhanced in arthritic condition due to activation of OC differentiation, and miR-223 is intensely expressed in rheumatoid arthritis (RA) synovium, particularly in monocyte/macrophage and CD4+ T-cell subsets." (PMID 30899258, 2019). "Previous studies have reported the up-regulation of the two-pore domain K+ channel K2P5.1 in the CD4+ T cells of patients with multiple sclerosis (MS) and rheumatoid arthritis (RA), as well as in a mouse model of inflammatory bowel disease (IBD)." (PMID 31861667, 2019). "The cytokine signaling system is closely related to the pathogenesis of rheumatoid arthritis, when T cells are activated and CD4+ T cells infiltrate the synovium of patients with RA." (PMID 31998324, 2019). "Multicolor flow cytometry was used to determine the circulating Th subsets among CD4+ T lymphocytes in 40 patients with rheumatoid arthritis before abatacept treatment." (PMID 31747403, 2019). "Anti-TNF-α agents have been shown to induce IL-17 expression in CD4 T cell from patients with juvenile idiopathic arthritis or rheumatoid arthritis." (PMID 31475008, 2019).
rheumatoid arthritis (continued). "Patients with rheumatoid arthritis treated with Abatacept show increased IL-10 by producing CD4+CD25-LAG3+ Treg cells." (PMID 31582900, 2019). "Abnormal genome-wide DNA methylation patterns have been revealed in CD4+ T cells from Chinese Han patients with rheumatoid arthritis." (PMID 31611879, 2019). "The monoclonal antibody studied was hIgG1-CD4 or Campath-9, which is a humanized IgG1-type antibody against CD4 antigen and which has been used in human clinical trials for the treatment of rheumatoid arthritis and psoriasis." (PMID 31671843, 2019). "In chronic inflammatory diseases, such as rheumatoid arthritis, a hyperactivity of CD4+ T helper cells has also been described to play a crucial role." (PMID 30428512, 2018). "NKG2D+ CD4+ T cells were initially found on peripheral blood and synovial fluid from rheumatoid arthritis (RA) patients, putatively as result of increased TNF-α and IL-15 levels in this disease." (PMID 29740438, 2018). "Here the authors show that a transcription factor, Sox4, induces the expression of CXCL13 in CD4 T cells in vitro, and is associated with ELS formation in patients with rheumatoid arthritis." (PMID 30232328, 2018). "In vivo, Sox4 is significantly upregulated in synovial CD4+ T cells, when compared with blood CD4+ T cells, from patients with rheumatoid arthritis (RA), and further correlates with ELS formation in RA synovium." (PMID 30232328, 2018). "Compared with healthy controls, the expression of PD-1 on peripheral CD4+ T cells was decreased among psoriatic and rheumatoid arthritis (RA) patients." (PMID 30069490, 2018). "Both approaches were effective for CD4+ T cells derived from patients with Ankylosing Spondylitis, Psoriatic Arthritis, Rheumatoid Arthritis as well as healthy controls." (PMID 30353145, 2018). "We then investigated the CD4 T cell response in seven patients treated with Ifx (n = 6) or Rtx (n = 1) (one with granulomatous uveitis; five with Crohn’s disease, and one with rheumatoid arthritis) having developed ADAs against Ifx or Rtx." (PMID 28529511, 2017). "This assumption is based on previous reports which demonstrated that synovial CD4+ T cells from rheumatoid arthritis patients were predominantly of ‘type 1’ polarity." (PMID 28388908, 2017). "Tregs, a subpopulation of CD4+ T cells, play a crucial role in maintaining immune homoeostasis and preventing the development of many inflammatory diseases, such as rheumatoid arthritis, multiple sclerosis, and ischemic stroke." (PMID 29197398, 2017). "Lastly, ASH1L, FOXP3 and SMAD3 are downregulated in peripheral CD4+ T cells from patients with rheumatoid arthritis." (PMID 28598443, 2017). "The pro‐inflammatory role of CD4+ NKG2D+ T cells was observed in patients with rheumatoid arthritis 5, 6, multiple sclerosis 11, Crohn's disease 8, 9, 10, granulomatosis with polyangiitis 7 and CMV infection." (PMID 28224733, 2017). "A reduction of CD4+ to CD8+ T cells ratio in patients with rheumatoid arthritis when as little as 2.5mg of prednisolone was administered every 6hrs has been reported." (PMID 28991896, 2017). "The aim was to investigate CD4+T-cell subsets, immune cells and their cytokine profiles in blood and synovial compartments in rheumatoid arthritis (RA) and inflammatory osteoarthritis (OA) to define specific immune signatures." (PMID 28526072, 2017). "These cells are a lineage of CD4+ T cell that produces IL‐17 and appears to have a pathophysiological role in certain inflammatory diseases (e.g., multiple sclerosis, rheumatoid arthritis, psoriasis)." (PMID 29226084, 2017). "And, HDAC4 is one of the most hyper-methylated genes outside the MHC region on CD4+ T cells from rheumatoid arthritis patients." (PMID 28177888, 2017).
rheumatoid arthritis (continued). "We found recently that baseline signal transducer and activator of transcription 3 phosphorylation in peripheral blood CD4+ T cells of patients with early rheumatoid arthritis (RA) is associated with treatment response to synthetic disease-modifying antirheumatic drugs (DMARDs)." (PMID 28399940, 2017). "Recent studies demonstrate that Th17 cells, a subtype of CD4+ T helper cells, play a critical role in many autoimmune and inflammatory diseases such as multiple sclerosis (MS), rheumatoid arthritis (RA), psoriasis and inflammatory bowel disease (IBD)." (PMID 27308096, 2016). "This increase in senescence‐like CD4+ T cells is also observed in patients with chronic infections and autoimmune diseases such as rheumatoid arthritis (RA)." (PMID 26910559, 2016). "We have shown the infiltration of CD56+ CD28null CD4+ T cells in extra-articular lesions in rheumatoid arthritis." (PMID 27933066, 2016). "In a TNFα-rich environment, such as in the case of rheumatoid arthritis, we found that anti-TNF therapy prevents the TNFα-induced loss of CD28 on the residual CD28+ CD8+ and CD4+ T cells, but the numbers of CD28null T cells remain the same." (PMID 27933066, 2016). "In the ectopic lymphoid‐like structures present in chronic inflammatory conditions such as rheumatoid arthritis, a subset of human effector memory CD4+ T cells that lacks features of follicular helper T (Tfh) cells produces CXCL13." (PMID 26541894, 2016). "For example, EGCG was reported to sensitize HUVEC to ischemia/reperfusion, rheumatoid arthritis synovial fibroblasts to tumor necrosis factor α, and CD4+ T cells to interferon γ." (PMID 26375285, 2015). "T cells (especially CD4+ T cells), monocytes and B cells are considered to be involved in the pathogenesis of rheumatoid arthritis (RA)." (PMID 25604867, 2015). "For example, immunotherapies enhanced Helios expression in CD4+ Tregs in the responder group of rheumatoid arthritis patients." (PMID 26343373, 2015). "In rheumatoid arthritis (RA), both CD4 and CD8 single positive (SP) T cells are known to be involved in the pathogenesis, but the role of peripheral CD4CD8 DP T cells has not been investigated in detail." (PMID 24667579, 2014). "Lck promoter-directed expression of the human transgene also causes no alteration in thymic repertoire or increase in disease severity in a model of rheumatoid arthritis, which depends on skewed thymic selection of CD4+ T cells." (PMID 24498279, 2014). "In the literature, LIGHT was reported in rheumatoid arthritis erosive bone-disease as expressed by synovial CD4+ T-cells as well as PB and synovial fluid CD14+ monocytes and CD20+ B-cells." (PMID 25460501, 2014). "It has been shown that CD4+ T cells of rheumatoid arthritis patients express higher levels of CD28 and other markers of activated T cells than those of healthy controls." (PMID 24205378, 2013). "In studies conducted in patients with active rheumatoid arthritis, peripheral blood CD4+CD25+ Tregs have shown reduced FOXP3 expression and suppressive function which can be reversed by treatment with an anti-TNFα monoclonal antibody (infliximab)." (PMID 24063002, 2013). "Increased frequencies of CD28-negative CD4 and CD8 T cells expressing NK cell-associated receptors are a common finding in autoimmune diseases, in particular rheumatoid arthritis." (PMID 23761790, 2013). "The CXCL16-CXCR6 system is involved in the pathogenesis of several inflammatory disorders including rheumatoid arthritis and chronic liver inflammation by recruiting CD4+ and CD8+ T cells." (PMID 23840334, 2013). "In contrast, circulating CD4+CD161+T-cells were decreased in newly diagnosed rheumatoid arthritis patients." (PMID 24223933, 2013). "We have recently demonstrated that calpain activity is increased in the B-CLL leukemic cells, in the CD4+ T cells of rheumatoid arthritis patients and in acute childhood leukemia blasts (in preparation)." (PMID 23835405, 2013).
rheumatoid arthritis (continued). "miRNA-146a is upregulated, whereas miR-363, miR-498 are downregulated in rheumatoid arthritis CD4+ T-cells and miR-146a is involved in the suppression of apoptosis and play a role in rheumatoid arthritis pathogenesis." (PMID 24454381, 2013). "Activated CD4+ T cells play a significant role in several autoimmunologic disorders such as rheumatoid arthritis and in the postoperative response." (PMID 23052508, 2013). "CD4+CD28null T-cells, extremely unusual in healthy adults, are expanded in chronic inflammatory disorders such as rheumatoid arthritis." (PMID 23762872, 2013). "In rheumatoid arthritis patients, decreased expression of miR-498 has been found in CD4+ T cells from synovial fluid or peripheral blood." (PMID 23418466, 2013). "ICOS has been found to be highly expressed on activated CD4+ T cells in patients with autoimmune conditions such as rheumatoid arthritis (RA), SLE, and inflammatory bowel disease." (PMID 24000287, 2013). "Similar findings were reported in effector CD4+ T cells recovered from synovial fluid of human rheumatoid arthritis patients." (PMID 22363608, 2012). "The study by Catalano was the first to report on the defective expression of sema3A in CD4 T cells derived from patients with rheumatoid arthritis (RA)." (PMID 22697500, 2012). "Tim3, like Tim1, has also been associated with a number of human diseases including multiple sclerosis and rheumatoid arthritis, and has been shown to be expressed on CD4+ Th1 cells in mice." (PMID 21470319, 2011). "Paradoxically, rheumatoid arthritis develops in humans in the presence of CD4+CD25+ Treg cells, and Treg cells are enriched at primary sites of autoimmune pathology." (PMID 21483764, 2011). "Exogenous IL-10 can suppress the in vitro development of Th17 cells from CD4+ T cells in patients with rheumatoid arthritis." (PMID 22176654, 2011). "Treatment with an antibody against CD4 suppresses the onset of rheumatoid arthritis, suggesting a role for CD4 T cells in disease progression." (PMID 21483764, 2011). "The aim of the study was to investigate the expression pattern and function of miRNAs in CD4+ T cells from patients with rheumatoid arthritis (RA)." (PMID 20459811, 2010). "TH17-expressing CD4+ cells were found to accumulate within rheumatoid synovial tissue and in rheumatoid arthritis synovial fluid." (PMID 18433499, 2008). "In rheumatoid arthritis, inflammation and degradation of synovial tissue are initiated by the influx of lymphocytes (B cells, CD4+, CD8+ and T cells)." (PMID 18959802, 2008). "In established rheumatoid arthritis (RA), highly differentiated CD4+ T lymphocytes persist within synovial tissue, and are prevented from undergoing apoptosis by high local concentrations of type I interferons." (PMID 18433499, 2008). "Together these data imply a primary role for CD4+CD28null T cells in manifestations elsewhere than in the joints of patients with HCMV-seropositive rheumatoid arthritis." (PMID 17825098, 2007). "This study shows that CD4+CD28null T cells express Toll-like receptors recognizing bacterial lipopolysaccharides in ankylosing spondylitis, psoriatic arthritis and rheumatoid arthritis." (PMID 16277694, 2005). "In adjuvant arthritis, a model for rheumatoid arthritis, we found that the percentage of CD4+ T cells expressing the activation marker CD134 (OX40 antigen) was elevated before disease onset." (PMID 15899047, 2005). "The high numbers of CD4+/CD28- T-cells found in patients with rheumatoid arthritis are consistent with this theory." (PMID 15613231, 2004). "This integration across CD4+ naïve/central‐memory, CD8+ effector‐memory, CD8+ naïve/central‐memory, and natural killer cells identified HS as having a consistent risk direction for GSDMA, and rheumatoid arthritis as having an overall protective direction." (PMID 41442179, 2026).
rheumatoid arthritis (continued). "To gain a deeper understanding of how these tolDC types exert their regulatory effects, we co-cultured them with CD4+ T cells from rheumatoid arthritis patients or healthy controls and analysed the gene expression profile and function of the responding T cells." (PMID 41497979, 2025). "Interestingly this profile resembles that of the CD4+ T cells obtained from joints of rheumatoid arthritis (RA) patients." (PMID 38332201, 2024). "Furthermore, Th17 and Treg, the subsets of CD4+ T helper cells, and particularly their balance play a pivotal role in rheumatoid arthritis." (PMID 38892148, 2024). "Bystander activation of memory CD8+ T cells has been shown to influence disease severity in several disease settings including rheumatoid arthritis, hepatitis, and COVID-19 (21, –23), but whether CD4+ T cells can play a similar role is unknown." (PMID 38838013, 2024). "Furthermore, we observed the activation of 4-1BB signaling in CD8+ T cell after BrQ treatment, while the agonistic anti-4-1BB monoclonal antibody can suppress antigen-specific CD4+ T cells by activating CD8+ T cells in rheumatoid arthritis animal models." (PMID 39068463, 2024). "In rheumatoid arthritis, MAGMA across five ancestry groups identified 34 novel loci, and multiancestry fine‐mapping identified a putative causal variant at the LEF1 locus, which is of interest as LEF1 has a role in CD4+ T cells, which are relevant to rheumatoid arthritis biology." (PMID 39022911, 2024). "Citrullinated proteins transform into neoantigens upon formation and present themselves to CD4+ T lymphocytes through major histocompatibility complex (MHC) class II molecules, particularly HLA-DRB1 alleles, which significantly correlate with rheumatoid arthritis susceptibility." (PMID 39530095, 2024). "As an example, autoimmune actively proliferating CD4+ T cells from patients with rheumatoid arthritis (RA), use glucose and the Pentose Phosphate Pathway (PPP) to generate intracellular reducing conditions (NADPH) and low ROS levels that keep the inflammatory condition going." (PMID 36670995, 2023). "Indeed, autoreactive CD4+ effector T cells that react with CV have been observed in patients with rheumatoid arthritis, suggesting that the induction of an anti-CV autoantibody is mediated by a T cell response to CV." (PMID 37190018, 2023). "Thus, we obtained peripheral blood from healthy donors and rheumatoid arthritis patients, and CD4+ T lymphocytes were purified and cultured for 5 days in the presence of anti-CD3/CD28 beads and recombinant interleukin-2 (IL-2)." (PMID 36902005, 2023). "This suggests that the dysregulation of eEF2K and its impact on CD4+ T cell function, including the promotion of Th17 profiles, may contribute to the pathogenesis of diseases like rheumatoid arthritis." (PMID 37875468, 2023). "So far, it has been confirmed, among others, that blocking the OX/OX40R interaction prevents the differentiation of CD4+ T cells and the development of inflammation in models of multiple sclerosis, autoimmune diseases of the gastrointestinal tract, GvHD, rheumatoid arthritis and atopic dermatitis." (PMID 37887878, 2023). "Besides, in patients with rheumatoid arthritis, increased relative abundance of gut genus Blautia was related with lower levels of T cells, B cells, CD4+ T cells, and Tregs." (PMID 38075899, 2023). "In support of this model, new findings have demonstrated that Orai3 expression is increased in CD4+ T cells from patients with rheumatoid arthritis and psoriatic arthritis and that silencing of Orai3 reduces tissue inflammation in a human synovium adoptive transfer model." (PMID 36803766, 2023). "Furthermore, studies utilizing CTLA-4-Ig (abatacept) to treat type 1 diabetes and rheumatoid arthritis have shown a reduction in the frequency of CD4+ Tregs in these patients." (PMID 36761170, 2022).